WIF1 (Wnt inhibitory factor 1)
Diseases named in the same sentence as WIF1 in open-access papers (continued):
Sharing a sentence is not in itself a finding about the gene and the disease.
breast carcinoma (continued). "After validating the effects of ISL on limiting breast CSCs, we continued to examine whether ISL could exert stimulatory effects on WIF1 in breast cancer cell lines." (PMID 25918249, 2015). "In breast cancer, this downregulation could be attributed to hypermethylation of the WIF1 promoter, as demonstrated both in breast cell lines and in primary breast carcinomas." (PMID 19570204, 2009). "In breast cancer, several genes encoding inhibitors of canonical Wnt/β-catenin signalling have been reported to be frequently hypermethylated, for example, SFRP1, SFRP2, SFRP5, WIF1 and DKK1." (PMID 18826564, 2008). "WNT antagonists may act as tumour suppressors and cause constitutive activation of WNT signalling when mutated; reduced expression of the secreted WNT inhibitors SFRP1 and WIF1 have been observed in breast cancers." (PMID 16933995, 2006). "Furthermore, curcumin decoration with chitosan nanoparticles strongly affected Wnt/β-catenin pathway by reducing β-catenin and increasing WIF1 gene in almost all three breast cancer cell lines, the findings that need to be further investigated in different cancers as well as in vivo conditions." (PMID 38365810, 2024). "Both results revealed that ISL could stimulate WIF1 expression in both breast cancer cell lines." (PMID 25918249, 2015). "A phase Ib clinical trial in HER2– breast cancer patients identified a four-gene signature (FBXW2, CCND2, CTBP2, and WIF1) as a potential predictive biomarker for the response to combined treatment with paclitaxel and vantictumab." (PMID 32083079, 2020). "Many members of this module, including WIF1, WNT1, SFRP1, FZD9, and FZD8 were hypermethylated and underexpressed in both luminal-A and luminal-B breast cancers but exhibiting larger deviations in DNAm and mRNA expression in the luminal-B subtype." (PMID 26664652, 2015). "In the present study, seven potential breast cancer marker candidates (SFRP1, SFRP2, SFRP5, WIF1, DKK3, ITIH5, and RASSF1A) were studied with regard to early breast cancer detection in serum." (PMID 23320751, 2013). "WIF1 and DKK3 promoter methylation were assessed by methylation-specific PCR with bisulfite-converted DNA from 19 normal breast tissues and 150 primary breast carcinomas." (PMID 19570204, 2009). "WIF1 and DKK3 promoter methylation were detected in 63.3% (95/150) and 61.3% (92/150) of breast carcinoma samples, respectively." (PMID 19570204, 2009). "Although the Wnt antagonist genes WIF1 and DKK3 show a very similar frequency of promoter methylation in human breast cancer, only DKK3 methylation proves as a novel prognostic marker potentially useful in the clinical management of this disease." (PMID 19570204, 2009). "Hence, combination of SOSTDC1, DACT2 and WIF1 was effective in differentiating breast cancer [non-invasive and invasive] from benign diseases of the breast and healthy individuals and could help as a complementary diagnostic tool for breast cancer." (PMID 34997107, 2022). "Moreover, multivariate diagnostic analysis of the methylation status of WIF1, Sostdc1, and DACT2 showed up to 91% specificity and 100% sensitivity in discriminating breast cancer (invasive and non-invasive) from benign tumours and controls and may be a complementary tool for breast cancer diagnosis." (PMID 36338475, 2022). "The results show that high expression of TCF7, AXIN2 and WIF1 all predict shorter relapse-free survival (RFS) in HER2-amplified breast cancer, but longer RFS in HER2-non-amplified disease." (PMID 34003256, 2021). "Additionally, miR-374a activates Wnt/β-catenin signaling by directly targeting WIF1, PTEN, and WNT5A, thereby promoting breast cancer metastasis." (PMID 32674274, 2020). "Methylation-sensitive high-resolution melting was used to screen promoter methylation in a panel of 13 genes reported as methylated in breast cancer (RASSF1A, TWIST1, APC, WIF1, MGMT, MAL, CDH13, RARβ, BRCA1, CDH1, CDKN2A, TP73, and GSTP1) in 29 tumour pairs (16 ipsilateral and 13 contralateral)." (PMID 26452468, 2015).
breast carcinoma (continued). "We here demonstrate for the first time that DKK3 methylation, but not WIF1 methylation, is an independent prognostic factor indicating poor patient survival in human breast cancer." (PMID 19570204, 2009). "In the present study, we addressed the question to whether promoter methylation of two Wnt antagonist genes (WIF1 and DKK3), that were previously reported as hypermethylated in breast cancer, provides prognostically relevant information in this tumor entity." (PMID 19570204, 2009). "Meanwhile, flow cytometry results also demonstrated that WIF1 inhibition could reverse the down-regulation of breast CSCs induced by ISL in MDA-MB-231 breast cancer cells, but an isotype-matched IgG at 4 μg/ml did not." (PMID 25918249, 2015). "Although WIF1 is similarly frequent hypermethylated like the Wnt antagonist gene DKK3, and neither gene methylation is associated with relevant clinicopathological factors, DKK3 methylation is an independent prognostic factor in breast cancer patient survival, whereas WIF1 methylation is not." (PMID 19570204, 2009). "Unfortunately, in their study the WIF1 promoter regions investigated by MSP and BGS were not matching or overlapping, so we decided to analyze WIF1 promoter methylation in breast cancer by MSP in the particular promoter region that has been covered by BGS in the other study." (PMID 19570204, 2009).
osteosarcoma (33 papers, 2010 to 2023). A usually aggressive malignant bone-forming mesenchymal neoplasm, predominantly affecting adolescents and young adults. "In osteosarcomas, silencing of WIF1 by promoter hypermethylation was associated with loss of differentiation and increased proliferation." (PMID 24289328, 2013). "In particular, hypermethylation of the WIF1 promoter, leading to WIF1 silencing (and thus activation of Wnt/beta-catenin signaling), was shown to be associated with various types of cancers including osteosarcoma, which indicated the association of WIF1 with osteoporotic diseases." (PMID 31139657, 2019). "In addition, the recent report has identified epigenetic silencing of WIF1 in some human osteosarcomas associated with upregulation of Wnt signaling." (PMID 25999350, 2015). "In the osteosarcoma case versus the angiosarcomas and intimal sarcomas, the Wnt inhibitory factor 1 (WIF1) was also upregulated." (PMID 36673024, 2023). "An earlier study showed that Wnt inhibitory factor 1 (WIF1) is epigenetically silenced in human osteosarcoma and that targeted disruption in mice accelerates osteosarcomagenesis." (PMID 34439353, 2021). "Conversely, inactivation of Wnt inhibitory factor 1 (Wif-1) has been closely correlated with radiation-induced osteosarcoma." (PMID 34130697, 2021). "Previous studies have demonstrated that miR-552 functions as a potential oncogene in a series of cancer types and figure out several downstream targets, such as AJAP1 in liver cancer, Smad2 and DACH1 in colorectal cancer, TIMP2 and WIF1 in osteosarcoma 28-32." (PMID 33867818, 2021). "Overexpression of various Wnt components such as Frizzled receptor and Wnt ligands, secreted Frizzled-related protein 3 (SFRP-3), and Wnt inhibitory factor-1 (WIF-1) have been reported in osteosarcoma." (PMID 34671398, 2021). "That is because in osteosarcoma, WIF1 knockdown rescued proliferation, migration and invasion of osteosarcoma cells." (PMID 32564237, 2020). "A study involving the use of osteosarcoma cell lines has found that WIF1 suppressed cellular proliferation by suppressing the canonical Wnt pathway." (PMID 31698687, 2019). "Silencing of Wnt inhibitory factor 1(WIF1), p14ARF, and RASSF1A by DNA hypermethylation and loss-of-imprinting in IGF2 and H19 have also been shown to occur in osteosarcoma." (PMID 26802029, 2016). "For example, Kansara and colleagues reported that WIF1 is epigenetically silenced in human osteosarcoma cell lines." (PMID 27049730, 2016). "Consistently, the expression of Wnt/β-catenin inhibitors is often suppressed in osteosarcoma including sFrzB and WIF1." (PMID 25999350, 2015). "It was also shown that the Wnt inhibitory factor 1 is epigenetically silenced in human osteosarcoma, and its disruption accelerates osteosarcoma development in mice." (PMID 23383046, 2013). "One recent finding is that Wnt-inhibitory factor-1 (Wif1) functions as a tumor suppressor in osteosarcomas." (PMID 21403899, 2011). "Additionally, inactivation of the Wnt antagonist, WIF1, has been related to radiation-induced osteosarcoma in mice, further suggesting the deregulation of Wnt signaling in osteosarcomas." (PMID 37176108, 2023). "WIF-1 is epigenetically silenced in human osteosarcoma cell lines and most primary cultures." (PMID 35052478, 2022). "Curiously, Wif1-KO mice are more susceptible to spontaneous and radiation-induced osteosarcomas, but not other cancer types." (PMID 35052478, 2022). "In osteosarcoma cell, miR-552 also facilitates tumor progression via targeting WIF1." (PMID 35465017, 2022). "miR-552-5p facilitates osteosarcoma cell proliferation and metastasis by targeting WIF1, which means miR-552-5p may become a new target for the treatment of osteosarcoma." (PMID 32095316, 2020).
osteosarcoma (continued). "WIF1 silencing by hypermethylation and consequent Wnt signaling activation has been demonstrated in numerous cancers such as nasopharyngeal cancer, lung cancer, mesothelioma, breast cancer, urinary bladder cancer, renal cancer, osteosarcoma and gastric cancer." (PMID 20573255, 2010). "Targeted deletion of mouse WIF1 augmented spontaneous and radiation-induced osteosarcoma formation." (PMID 20573255, 2010). "Also the miR-552-5p promoted osteosarcoma development and progression by inhibiting WIF1." (PMID 34627187, 2021). "In addition, decreased WIF1 expression in CC was consistent with some previous studies which were based on human tumor study, such as gastrointestinal tract, kidney, glioblastoma, osteosarcoma, lung, pituitary, bladder, and oral cavity." (PMID 27843945, 2016). "Inhibition of Wnt signaling by overexpression of secreted Wnt antagonists soluble LRP5, Frzb, and WIF1 markedly down-regulated mRNA and protein expression of NRP2 in osteosarcoma cell lines." (PMID 25890345, 2015).
colorectal cancer (29 papers, 2011 to 2025). A primary or metastatic malignant neoplasm that affects the colon or rectum. "A study on colorectal cancer showed that DNMT1 overexpression is associated with promoter methylation of WNT pathway regulators that include WNT inhibitory factor-1 (WIF1), adenomatous polyposis coli (APC), and Dickkopf-3 (DKK3)." (PMID 36765652, 2023). "The aim of our meta-analysis was to summarize the diagnostic value of WIF1 methylation in colorectal cancer (CRC)." (PMID 29435185, 2018). "Here, we developed the ColoCaller test, which simultaneously detects the methylation status of the SDC2, TFPI2, WIF1, and NDRG4 genes in stool DNA, to optimize the screening of gastric and colorectal cancer in high-risk populations." (PMID 35419280, 2022). "Relevant to the second explanation, it has been reported that restoration of WIF1 expression in colorectal cancer cell lines can induce significant apoptosis in these cells, despite the fact that they are known to carry WCP downstream mutations." (PMID 33477402, 2021). "Hypermethylation of WIF1 CpG islands is considered to be a sensitive marker of colorectal cancer cells." (PMID 32766143, 2020). "Hsa-miR-374a-5p interferes with carcinogenesis by regulating Srcin1, which contributes to the growth and metastasis of colorectal cancer, or by regulating WIF1 that acts as tumor suppressor." (PMID 29293623, 2018). "WIF1 was a secreted inhibitory factor of Wnt pathway, which played a pivotal role in blockade of Wnt signaling and induced apoptosis in colorectal cancer cells." (PMID 28977860, 2017). "It has been reported that WIF-1 expression is down regulated in several human cancer including prostate, bladder, breast, nonsmall-cell lung carcinomas and colorectal cancer." (PMID 24755295, 2014). "Univariate analysis indicates that WIF1 promoter methylation is prognostic factors for overall survival in colorectal carcinomas." (PMID 25107489, 2014). "In the present study, we propose a panel of tumor-specific methylation genes (NPY, PENK, and WIF1) which in combination show a potential as epigenetic markers for the colorectal cancer diagnosis." (PMID 24289328, 2013). "In addition, expression of Wif1, an intermediate of Wnt signaling, and IFITM3 are increased in a colorectal cancer induction model—supporting a functional relationship between Wif1 and IFITM3 in cancer initiation." (PMID 33364194, 2020). "As a secreted lipid binding protein that binds to Wnt proteins and inhibits Wnt signaling pathway, Wnt inhibitory factor-1 (WIF-1) is identified as a direct and functional target of miR-181a in colorectal cancer, and an ectopic expression of miR-181a promotes tumor growth and liver metastasis." (PMID 29977206, 2018). "It has been reported that colorectal cancer patients with ZNF331 methylation have poor overall survival, and WIF1 methylation is negatively correlated with prognosis in oesophageal cancer." (PMID 33992091, 2021). "Another relevant target was WIF1 (−652, TSS), a key inhibitor of the WNT/β-catenin signaling pathway involved in the RPE cell fate specification and an onco-suppressor gene that is epigenetically silenced by DNA hypermethylation in colorectal cancer and hepatocellular carcinoma." (PMID 40565279, 2025). "Thus, the hypermethylated promoters of NPY and WIF1 are specific early markers of colorectal cancers but their roles in CRCS carcinogenesis are not clearly established." (PMID 34627187, 2021). "Quantitative methylation-specific PCR (qMSP) was used to evaluate methylation of four Wnt-antagonists, SFRP2, WIF-1, DKK3 and SOX17 in 18 normal colorectal mucosa samples, 9 colorectal cancer cell lines, 18 carcinomas, 44 nonpolypoid and 44 polypoid adenomas." (PMID 24350795, 2013).
pancreatic cancer (22 papers, 2007 to 2025). "For instance, exosomal hsa_circ_0030167 derived from bone marrow MSCs suppressed the progression and stemness of pancreatic cancer cells by sponging miR‐338‐5p to regulate the downstream wif1/Wnt8/β‐catenin axis." (PMID 39901896, 2025). "ALKBH5 also promotes Wnt inhibitory factor 1 (WIF-1) transcription, suppressing Wnt signaling in pancreatic cancer cells and inhibiting cancer progression." (PMID 38856795, 2024). "The overexpression of ALKBH5 can sensitise pancreatic cancer to chemotherapy, which is dependent on enhancing the expression of WIF‐1 and activating Wnt signalling." (PMID 35696608, 2022). "HOTAIR inhibition increased the expression of WIF-1 (Wnt inhibitory factor 1) and enhanced radiosensitivity of pancreatic cancer cells." (PMID 34178644, 2021). "ALKBH5 was reported to inhibit pancreatic cancer tumorigenesis by decreasing WIF-1 RNA methylation through mediating Wnt signaling." (PMID 34345203, 2021). "In TME, ALKBH5 overexpression can inhibit pancreatic cancer by decreasing the level of m6A RNA modification of WIF-1, blocking the activation of Wnt signaling, and increasing the sensitivity of pancreatic cancer cells to drugs." (PMID 34660577, 2021). "ALKBH5 overexpression repressed pancreatic cancer tumorigenesis by reducing WIF-1 RNA methylation and inactivating Wnt signaling." (PMID 34491904, 2021). "ALKBH5 overexpression blocked this pathway by m6A demethylation-mediated upregulation of Wnt inhibitory factor-1 (WIF-1) which in pancreatic cancer was overcome by ALKBH5 downregulation." (PMID 33814008, 2021). "In the current study, higher expression of WIF1 was observed aftertreatment with Betatrophin in the MiaPaca-II and Panc-1 pancreatic cancer celllines." (PMID 32745158, 2020). "Inline with our study, down-regulation of the WIF1 gene was observedin pancreatic cancer tissues, and this was attributed to hypermethylation of theWIF1 promoter region." (PMID 32745158, 2020). "Down-regulation of Wif1 mRNA expression is observed in esophageal, gastric, colorectal, and pancreatic cancers." (PMID 17506908, 2007). "However, ALKBH5 overexpression sensitized pancreatic cancer cells to gemcitabine therapy and inhibited pancreatic cancer tumorigenesis by reducing the levels of m6A-dependent WNT inhibitory factor 1 (WIF-1) and hindering WNT signaling activation." (PMID 32398132, 2020). "Taken together, it is plausible to say that Betatrophin has an anticancer effect onthe pancreatic cancer cell lines used in this study, MiaPaca-II and Panc-1, byinhibiting cell growth and increasing WIF1 gene expression, whichsubsequently reduces Wnt signaling as a decisive pathway in proliferation." (PMID 32745158, 2020). "ALKBH5 upregulates Wnt inhibitory factor 1 (WIF‐1) expression by removing m6A of WIF‐1 mRNA and inhibits pancreatic cancer progression by suppressing the Wnt pathway." (PMID 40448344, 2025). "In pancreatic cancer, ALKBH5 relies on the demethylation of Wnt inhibitory factor 1 (WIF-1) and the activation of Wnt signal to inhibit tumorigenesis and make tumor cells more sensitive to chemotherapy." (PMID 33552994, 2020). "However, in pancreatic cancer, ALKBH5 regulates the expression of Wnt inhibitory factor 1 (WIF-1) and inhibits the downstream Wnt signaling pathway." (PMID 40603319, 2025). "Also, after radiotherapy, HOTAIR down-expression by overexpression of Wnt inhibitory factor 1 (WIF-1) and autophagy related 7 (ATG7) reduces radio-resistance and cell proliferation and induces apoptosis in pancreatic cancer patients." (PMID 38559560, 2024). "Although, activation of theWnt pathway seems to be involved in pancreatic cancer, the expression and precisefunction of WIF1 in pancreatic cancer progression have not beendetermined so far." (PMID 32745158, 2020).
bladder cancer (16 papers, 2009 to 2023). "Knockdown of WIF1 by siRNA in bladder cancer cell lines led to increased activity in c-myc and cyclin D1 mRNA transcription and increased cell growth." (PMID 33672668, 2021). "CpG hypermethylation of the WIF1 (Wnt inhibitory factor-1) promoter was found to lead to decreased transcription and increased Wnt signaling activity in human bladder cancer cell lines." (PMID 33672668, 2021). "Silencing of the WIF1 gene due to promoterhyper-methylation has been revealed in gastrointestinal, lung and bladder cancers.It has also been observed that stimulation of WIF1 activity incancer cells allowed to treat some malignant cancers." (PMID 32745158, 2020). "WIF1 was reported as frequent target of epigenetic inactivation in several tumors such as lung, prostate, breast, bladder cancers." (PMID 24289328, 2013). "Higher nuclear accumulation of β-catenin was observed that inversely correlated with the WIF-1 expression and the LOH close to the WIF-1 gene loci was found to be a rare event in bladder cancer." (PMID 22325146, 2012). "In addition, it has been confirmed that WIF1 (Wnt inhibitory factor-1), a Wnt pathway inhibitor, can inhibit human invasive urinary bladder cancer cells growth." (PMID 29420609, 2018). "Another group reported that the WIF-1 promoter was hypermethylated in bladder cancer that may contribute to the pathogenesis of bladder cancer through aberrant canonical Wnt/β-catenin signaling." (PMID 22325146, 2012). "In breast, lung, prostate and bladder cancer, WIF1 expression was found to be frequently downregulated, suggesting it might represent a tumor suppressor gene." (PMID 19570204, 2009).